TSGA10IP (testis specific 10 interacting protein)
Synonyms: FLJ32880; FAM161C
Tractability: No criterion of Open Targets' tractability assessment is met for any kind of drug.
Gene: Protein-coding gene on chromosome 11 (65,945,480 to 65,959,966, forward strand). Ensembl gene ENSG00000175513.
Subcellular location (Human Protein Atlas): Mid piece
Gene Ontology:
Molecular function: protein binding
Biological process: cilium organization
Cellular component: photoreceptor connecting cilium; cytoskeleton
Genetic constraint (gnomAD): Loss-of-function variants: 64 observed, 60.39 expected, observed/expected ratio (o/e) 1.06, 90% interval 0.87 to 1.3. The upper end of that interval is the gene's LOEUF score, 1.3, which puts it in group 5 of 6, group 1 being the genes least tolerant of losing a copy. Missense variants: 681 observed, 687.17 expected, observed/expected ratio (o/e) 0.99, 90% interval 0.93 to 1.06. Synonymous variants: 316 observed, 285.19 expected, observed/expected ratio (o/e) 1.11, 90% interval 1.01 to 1.22.
Homologues: Orthologues: chimpanzee TSGA10IP (98% identical), macaque TSGA10IP (93% identical), dog TSGA10IP (65% identical), pig TSGA10IP (65% identical), mouse Tsga10ip (58% identical), rat Tsga10ip (56% identical), guinea pig Tsga10ip (27% identical), Caenorhabditis elegans famh-161 (7% identical). Paralogues in human: FAM161A (17% identical), FAM161B (17% identical).
Diseases named in the same sentence as TSGA10IP in open-access papers:
TSGA10IP is named in the same sentence as 1 disease in open-access papers, as found by Europe PMC text mining. Sharing a sentence is not in itself a finding about the gene and the disease. The quoted sentences say what the papers report.
cancer (1 paper, 2015). A tumor composed of atypical neoplastic, often pleomorphic cells that invade other tissues. "It should be noted however, that TSGA10IP (TSGA10 interacting protein) interacts with TSGA10, a protein also associated with cancer and that binds cytoskeletal proteins (e. g., vimentin and actin-γ1)." (PMID 26569114, 2015).